RHOQ (ras homolog family member Q)
Description:
Plasma membrane-associated small GTPase which cycles between an active GTP-bound and an inactive GDP-bound state. In active state binds to a variety of effector proteins to regulate cellular responses. Involved in epithelial cell polarization processes. May play a role in CFTR trafficking to the plasma membrane. Causes the formation of thin, actin-rich surface projections called filopodia.
Synonyms: ARHQ; RASL7A; TC10; HEL-S-42; TC10A
Tractability: Small molecule: a structure with a bound ligand is known. Antibody: UniProt places it where antibodies can reach, with high confidence; its Gene Ontology location is reachable by antibodies, with high confidence. PROTAC: ubiquitination databases record sites on it.
Gene: Protein-coding gene on chromosome 2 (46,541,806 to 46,584,688, forward strand). Ensembl gene ENSG00000119729.
Subcellular location: Cytoplasm; Cell membrane
Subcellular location (Human Protein Atlas): Cytosol; Vesicles
Pathways (Reactome):
Signal Transduction: RHO GTPases regulate CFTR trafficking; RHOQ GTPase cycle
Vesicle-mediated transport: Translocation of SLC2A4 (GLUT4) to the plasma membrane
Gene Ontology:
Molecular function: GBD domain binding; GTPase activity; profilin binding; protein binding; protein kinase binding; G protein activity; GTP binding
Biological process: cellular response to insulin stimulus; cortical actin cytoskeleton organization; GTP metabolic process; insulin receptor signaling pathway; negative regulation of protein localization to plasma membrane; positive regulation of D-glucose import; positive regulation of filopodium assembly; positive regulation of transcription by RNA polymerase II; actin filament organization; endocytosis; establishment of cell polarity; regulation of actin cytoskeleton organization; actin cytoskeleton organization; small GTPase-mediated signal transduction
Cellular component: actin filament; extracellular exosome; plasma membrane; Golgi-associated vesicle membrane; cytoplasm; membrane raft
Genetic constraint (gnomAD): Loss-of-function variants: 3 observed, 16.28 expected, observed/expected ratio (o/e) 0.18, 90% interval 0.083 to 0.48. The upper end of that interval is the gene's LOEUF score, 0.48, which puts it in group 2 of 6, group 1 being the genes least tolerant of losing a copy. Missense variants: 113 observed, 160.57 expected, observed/expected ratio (o/e) 0.7, 90% interval 0.6 to 0.82. Synonymous variants: 76 observed, 64.16 expected, observed/expected ratio (o/e) 1.18, 90% interval 0.98 to 1.43.
Homologues: Orthologues: chimpanzee RHOQ (100% identical), dog RHOQ (100% identical), macaque RHOQ (100% identical), pig RHOQ (100% identical), mouse Rhoq (99% identical), tropical clawed frog rhoq (93% identical), zebrafish rhoq (90% identical), guinea pig RHOQ (87% identical). Paralogues in human: RHOJ (77% identical), CDC42 (64% identical), RAC1 (61% identical), RAC3 (60% identical), RAC2 (59% identical), RHOG (53% identical), RHOU (52% identical), RHOC (48% identical), RHOV (48% identical), RHOB (48% identical), RHOA (47% identical), RHOF (44% identical), and 10 more.
Diseases named in the same sentence as RHOQ in open-access papers:
RHOQ is named in the same sentence as 23 diseases in open-access papers, as found by Europe PMC text mining. Sharing a sentence is not in itself a finding about the gene and the disease. The quoted sentences say what the papers report.
colorectal cancer (7 papers, 2020 to 2025). A primary or metastatic malignant neoplasm that affects the colon or rectum. "For instance, common editing in the Ras homolog family member Q (RHOQ) promotes the invasion of colorectal cancer." (PMID 39641903, 2025). "A-to-G editing of Rho-related GTP-binding protein (RhoQ), which leads to N136S amino acid substitution, increases RhoQ activity and invasion by colorectal cancer." (PMID 38186576, 2023). "A study has illuminated that dysregulation of RNA editing in RHOQ contributed to the progression of colorectal cancer." (PMID 36843983, 2023). "In colorectal cancer, A-to-I RNA editing impacts Ras homolog family member Q (RHOQ) to promote invasion." (PMID 35133980, 2022). "For example, the A-to-I hyper-editing in RHOQ transcripts will induce the abnormal elevation of RHOQ protein, and thus promote the invasion and metastasis of cancer cells in colorectal cancer." (PMID 32117713, 2020). "In liver cancer, editing of the antizyme inhibitor AZIN1 induces its cytoplasmic-to-nuclear translocation to increase tumor aggressiveness, whereas in colorectal cancer, ATIRE impacts Ras homolog family member Q (RHOQ) to promote invasion." (PMID 36999050, 2023).
glioma (3 papers, 2015 to 2022). A benign or malignant brain and spinal cord tumor that arises from glial cells (astrocytes, oligodendrocytes, ependymal cells). "Seven Rho GTPases (RND1, RND3, RAC3, RHOA, RAC2, RAC1 and RHOC) showed a significantly greater connectivity in grade IV glioma and seven (CHP, RHOD, RHOF, RHOB, RHOQ, RND2, RHOBTB3) showed greater connectivity in grade II glioma." (PMID 26132659, 2015).
colon cancer (2 papers, 2024). "RHOQ isoforms generated by RNA editing can impact colon cancer invasion and recurrence by altering the cytoskeleton." (PMID 38493171, 2024). "Another instance of RNA editing affecting the cytoskeleton is RNA editing at the N136S site of the RhoQ GTPase enzyme RHOQ in colon cancer." (PMID 38493171, 2024).
melanoma (2 papers, 2015 to 2017). A malignant, usually aggressive tumor composed of atypical, neoplastic melanocytes. "The RhoQ transcription levels of 3 types of melanoma cells were lower than those of MC." (PMID 28404912, 2017). "While nothing is known about the role of RHOQ and RHOU in melanomagenesis, RHOJ participates to chemoresistance through DNA repair control and modulates metastasis potential in melanoma." (PMID 26098773, 2015).
colon adenocarcinoma (1 paper, 2022). "High expression of RHOQ promoted colon adenocarcinoma cell growth and was associated with a lower survival rate in patients with colon adenocarcinoma." (PMID 36185204, 2022).
female infertility (1 paper, 2021). Diminished or absent ability of a female to achieve conception. "APCDD1 is involved in adipogenic differentiation, CTDSP2 is a target gene of FOXO and regulates cell cycle progression, EZH2 is an important regulator in the female reproductive tract, MGA4A is involved in embryo lethality and female infertility, and RHOQ regulates mitochondrial function." (PMID 34639162, 2021).
cancer (9 papers, 2017 to 2025). A tumor composed of atypical neoplastic, often pleomorphic cells that invade other tissues. "With a more comprehensive antiviral system, we suspect that blocking one of them, the mevalonate/farnesylation/RHOQ pathway, would cause less devastating consequences to the antiviral system in normal cells, in contrast to cancer cells with a weak antiviral system." (PMID 29670091, 2018). "CDC42 family GTPases (RHOJ, RHOQ, CDC42) are upregulated but rarely mutated in cancer and control both the ability of tumor cells to invade surrounding tissues and the ability of endothelial cells to vascularize tumors." (PMID 35385746, 2022). "Here, we focus on CDC42 and RHOJ, two of the three CDC42 family members (CDC42, RHOJ, and RHOQ) that have the most defined roles in cancer." (PMID 35385746, 2022). "CDC42 family GTPases (RHOJ, RHOQ, CDC42) are linked to multiple human cancers and modulate cell-cycle progression, tumor cell migration/invasion, and tumor angiogenesis." (PMID 35385746, 2022). "Dependency score analysis by DepMap showed that ACTG1 and RHOQ were less essential across pan-cancer cells including COAD cell lines, and CCT6A, UTP18, YRDC, RRP12, RFT1, NLE1, as well as DDOST were essential across pan-cancer cells including most of COAD cell lines." (PMID 31867042, 2019). "As we demonstrated that the inhibition of mevalonate/farnesylation/RHOQ pathway selectively promotes the replication of the M1 virus in cancer cells, we proposed that blocking this pathway may substantially potentiate the therapeutic efficacy of the M1 virus." (PMID 29670091, 2018). "Fourteen of the mutated genes in this tumor are involved in metabolism (endogenous molecules as well as drugs), small molecule biochemistry, and cancer: AATF, ATF71P, CRIPAK, CROCC, CYP2A6, DOCK5, GPAT2, KRTAP4–9, LSM14A, MUC2, MYO1F, RHOQ, SUFU, and UTRN." (PMID 29259192, 2017). "In addition, CCT6A, UTP18, YRDC, RRP12, RFT1, NLE1, as well as DDOST were essential genes across pan-cancer including COAD cells, and ACTG1 and RHOQ were less essential genes in cancer cells." (PMID 31867042, 2019).
tumor (9 papers, 2017 to 2025). "Here, we have presented additional effortsof our drug discoveryprogram targeting the CDC42 GTPase (RHOJ, CDC42, and RHOQ) proteins,which are overexpressed in multiple tumor types." (PMID 37026468, 2023). "CDC42 GTPases (RHOJ,CDC42, and RHOQ) are overexpressed in multipletumor types and activate pathways critical for tumor growth, angiogenesis,and metastasis." (PMID 37026468, 2023). "The results showed that TRAF3IP3, WIPI1, ARHGAP11A, and RHOQ were significantly differentially expressed in normal and tumor tissue, displaying good classification performance." (PMID 36185204, 2022). "In order to test which intracellular factors reflect the oncolysis ability of OVM cooperating with the receptor MXRA8, we compared the oncolytic ability of OVM with the ZAP, ERN1 or RHOQ expression in several tumor cells using Spearman’s correlation." (PMID 35393389, 2022). "Finally, RHOQ, while less studied, is also known to promote tumor invasion and angiogenesis." (PMID 35385746, 2022).
infection (2 papers, 2017 to 2018). The state of being infected such as from the introduction of a foreign agent such as serum, vaccine, antigenic substance or organism. "Thus, we speculate that RHOQ may inhibit the entry and elimination process of M1 virus in the early stage of infection through V-ATPase and RAB GTPases, and more efforts are still needed to demonstrate the mechanism of RHOQ inhibiting M1 virus." (PMID 29670091, 2018).
RHOQ also shares sentences with these, for which no sentence is quoted: breast carcinoma (2 papers); glioblastoma (2); liver cancer (2); adenocarcinoma (1); breast tumor (1); diabetes (1); gastric cancer (1); hepatocellular carcinoma (1); influenza infections (1); Insulin resistance (1); lung carcinoma (1); lymphoma (1); mammary adenocarcinoma (1); oesophageal cancer (1).